TSPO (translocator protein)
Diseases named in the same sentence as TSPO in open-access papers (continued):
Sharing a sentence is not in itself a finding about the gene and the disease.
multiple sclerosis (59 papers, 2013 to 2026). A progressive autoimmune disorder affecting the central nervous system resulting in demyelination. "The contribution of TSPO PET in MS was also recently tackled in a “Controversies” section of the Multiple Sclerosis Journal." (PMID 34387719, 2021). "With respect to the microglial proteins monitored by PET tracers, the translocator protein 18 kDa (TSPO) has been targeted in neurological diseases, such as Alzheimer’s disease and multiple sclerosis." (PMID 34063598, 2021). "WM TSPO studies in rodents have been restricted to mouse models of multiple sclerosis, which have focally elevated TSPO in active demyelinating lesions." (PMID 32990808, 2020). "Despite the proved potential of both PET and MRI for the microglial imaging, very few studies have integrated both the modalities in humans and, generally, the majority use MRI to simply colocalize TSPO-uptake with multiple sclerosis plaques identified by MRI." (PMID 32327973, 2020). "Recently, Sridharan and co-workers confirmed specific binding of 18F-GE-180 in humans by a blocking study in patients with multiple sclerosis showing that in HAB subjects about 57% of VT represent specific binding of 18F-GE-180 to the TSPO." (PMID 32322915, 2020). "The second one, using a second-generation TSPO radiotracer in patients affected by multiple sclerosis, demonstrated microglial activation in both normal appearing cerebellum and segmented lesions." (PMID 32327973, 2020). "Positron emission tomography (PET) ligands targeting the translocator protein (TSPO) represent promising tools to visualize neuroinflammation in multiple sclerosis (MS)." (PMID 30696113, 2019). "This approach showed more consistent success using second-generation radioligands, with higher TSPO PET brain signal found in multiple sclerosis, ALS, mild cognitive impairment, and AD compared to controls." (PMID 31261683, 2019). "The colocalization of TSPO upregulation and activated glia has been observed in human degenerative disorders including AD, PD, multiple sclerosis (MS), (HD) and amyotrophic lateral sclerosis (ALS)." (PMID 28387722, 2017). "The loss of TSPO in experimental autoimmune encephalomyelitis (EAE) mice, an animal model of multiple sclerosis (MS), caused mild astrogliosis and less EAE clinical scoring." (PMID 27907096, 2016). "In a model of multiple sclerosis, TSPO is upregulated in microglia and astrocytes during neural inflammation." (PMID 24877623, 2014). "The knockout of TSPO induced a lower astrocyte reactivity and decreased the severity of symptoms in response to the experimental induction of multiple sclerosis, thereby supporting the pro-inflammatory hypothesis of TSPO in different pathological contexts." (PMID 41152868, 2025). "A recent study with multiple sclerosis patients indicated that increased TSPO signal in the human brain might rather reflect a high cell density of microglial cells and not their activation phenotype." (PMID 35008218, 2021). "Moreover, TSPO level is enhanced in multiple sclerosis, amyotrophic lateral sclerosis, Parkinson’s disease, Huntington’s disease, AD, and stroke." (PMID 29506545, 2018). "Upregulation of TSPO is seen in many CNS diseases, including Alzheimer's, Huntington's, brain tumours, traumatic brain injury, ischaemic stroke, frontotemporal dementia, amyotrophic lateral sclerosis, Parkinson's and multiple sclerosis (MS)." (PMID 23681668, 2013). "Finally, considering that major evidences emerged by TSPO uptake in multiple sclerosis patients, and the very low brain uptake in healthy subjects, several doubts have been raised for the blood–brain barrier permeability of these tracers in physiological conditions." (PMID 32327973, 2020). "Accumulating evidence has demonstrated increased TSPO expression during several neuroinflammatory conditions such as intracerebral hemorrhage and multiple sclerosis, suggesting that targeting TSPO may be a viable approach to limiting neuroinflammation and brain injury." (PMID 28754131, 2017).
multiple sclerosis (continued). "Of course, brain TSPO-PET signal is markedly upregulated in clinical conditions that have neuroinflammation at their core, such as Huntington’s disease or multiple sclerosis." (PMID 32152285, 2020). "Positron emission tomography (PET) using translocator protein (TSPO) ligands has been used to detect neuroinflammatory processes in neurological disorders, including multiple sclerosis (MS)." (PMID 29402285, 2018). "Here, we sought to determine the specific role of TSPO in experimental autoimmune encephalomyelitis (EAE), the most studied animal model of multiple sclerosis (MS)." (PMID 26925573, 2016). "As a microglia activation marker, TSPO PET visualizes neuroinflammation and has been established as a tool for imaging inflammatory CNS processes in neurodegenerative diseases or in multiple sclerosis." (PMID 36329288, 2023). "Recent positron emission tomography (PET) studies using TSPO radioligands such as [11C]PK11195 and [11C]PBR28 have indicated the usefulness of these PET biomarkers in patients with neuroinflammatory diseases, including multiple sclerosis (MS)." (PMID 23618062, 2013). "α-Mangostin reduced the levels of proinflammatory cytokine IL-6, COX-2, and 18 kDa translocator protein (TSPO) in the brain from LPS-induced neuroinflammation in C57BL/6J mice, which was considered as an adjuvant treatment in preclinical models of AD, PD, and multiple sclerosis." (PMID 32019180, 2020). "However, existing literature regarding TSPO expression on human activated macrophages is lacking, mostly deriving from brain tissue studies, including studies of brain malignancy, and inflammatory diseases such as multiple sclerosis." (PMID 28968465, 2017).
Stroke (55 papers, 2013 to 2025). Sudden impairment of blood flow to a part of the brain due to occlusion or rupture of an artery to the brain. "Plasma TSPO levels are also known to be intimately linked with disease progression and worse functional outcomes post-stroke." (PMID 34572529, 2021). "In this study, we measured the level of TSPO in acute ischemic stroke patients and determined its association with the degree of stroke severity and its ability to predict stroke functional outcomes." (PMID 30034558, 2018). "The level of TSPO within 24 h after an incident stroke was associated with the appearance of clinical worsening and poor functional outcomes at discharge." (PMID 30034558, 2018). "Plasma TSPO might reflect CNS inflammation after a stroke and may be intimately linked with disease progression and final outcomes, including clinical worsening and poor functional outcomes." (PMID 30034558, 2018). "The overexpression of the TSPO is associated with microglial activation caused by neuronal damage or neuroinflammation, and these activated microglia are involved in various CNS diseases that are known or suspected to involve inflammation, such as AD, PD, MS and strokes." (PMID 37111333, 2023). "Another study with stroke patients determined the plasma TSPO levels at the beginning and end of hospitalization." (PMID 41203762, 2025). "PET-TSPO studies in animals have shown an increase in TSPO expression following neuroinflammation induction, while studies in humans have reported upregulation of TSPO after stroke and traumatic brain injury near the lesion site." (PMID 38753646, 2024). "TSPO PET imaging during the subacute phase suggests that the inflammatory response is confined to the infarcted area in stroke patients, which then resolves within three months." (PMID 37193998, 2023). "Positron emission tomography imaging of inflammation targeting the mitochondrial translocator protein (TSPO) revealed localized neuroinflammation at 7 days after stroke compared to sham (3.8 ± 0.8 vs 2.6 ± 0.7 %ID/g max, p < 0.001)." (PMID 36279013, 2022). "In the present study, we characterized two mouse models of cerebral stroke using T2-weighted MRI to define the stroke focus and penumbra early after injury and TSPO-targeted PET to assess neuro- and cardiac inflammation." (PMID 36279013, 2022). "In rodents, the established temporal dynamics of 18F-DPA-714 in stroke indicate that the number of CD11b–positive TSPO–positive/Iba-1–positive TSPO–positive cells peaks at around days 11–14, correlating with the peak of radiotracer uptake." (PMID 34168016, 2022). "Higher inflammatory cell content in the stroke core and penumbra within the first days of ischemic damage identified non-invasively by PET imaging of TSPO is associated with a parallel increase in cardiac TSPO signal and impaired contractile function." (PMID 36279013, 2022). "PET imaging studies using TSPO tracers have shown increased brain uptake in post-stroke, although different time course and distribution were detected depending on the animal models and procedures." (PMID 34642898, 2022). "18F-DPA-714 PET has been used in many translational studies to track TSPO-dependent inflammatory reactions after stroke." (PMID 35115368, 2022). "Of note, there are several issues when considering TSPO as a marker for activated microglia in stroke." (PMID 35223925, 2022). "They found that acute MMP activation after stroke is preceding TSPO-dependent gliosis and that spatial distribution of MMPs and TSPO was regionally independent with only minor overlapping of the two tracers in peri-infarct regions." (PMID 33669804, 2021). "In human neuropsychiatric illnesses, such as AD, HIV encephalitis, multiple sclerosis, amyotrophic lateral sclerosis, frontotemporal dementia, and stroke, TSPO is expressed mainly in activated microglia and to a lesser extent in astroglia." (PMID 34052828, 2021).
Stroke (continued). "Decreases in TSPO in astrocytes correlate with decreases in the A1 pro-inflammatory phenotype in the brain post-stroke." (PMID 34572529, 2021). "The development of TSPO ligands and radiolabeled markers for TSPO expression provide two avenues of function for use in post-stroke patients." (PMID 34572529, 2021). "Generally, studies testing new TSPO radiotracers against the prototypic [11C]-R-PK11195 or more recent competitors use models of acute focal neuroinflammation (e.g. stroke or lipopolysaccharide injection)." (PMID 34245328, 2021). "The stroke effect on TSPO expression levels was observed by IHC, indicated by significant higher percentage of stained area within the infarct compared to the contralateral side for both dietary groups." (PMID 33754046, 2021). "The discovery of TSPO offers a new approach to diagnosing neuroinflammation, managing apoptosis, mitigating ROS, and regulating gene expression post-stroke." (PMID 34572529, 2021). "The improvement of stroke outcome at day 7 after daily treatment with ENBA was concomitant with the significant decrease of TSPO expression with [18F]DPA-714, supporting the role played by A1ARs on neuroinflammation after cerebral ischemia." (PMID 33391483, 2021). "The other major use of TSPO imaging in stroke models is to better understand the role of various neuroinflammation processes following experimental stroke." (PMID 34245328, 2021). "Other TSPO tracers have been evaluated using stroke models, such as [18F]VUIIS1008, [18F]VUIIS1008A and [18F]F-DPA." (PMID 34245328, 2021). "In 2015, Boutin and Pinborg published a review on the literature of TSPO-PET imaging in stroke covering brain ischaemia models and clinical studies." (PMID 34245328, 2021). "In stroke, blood−brain permeability leakage is an early and transient event after ischaemia and reperfusion whereas TSPO activation is increased 1−3 weeks later." (PMID 33937770, 2021). "TSPO immunohistochemistry-based cell counting was performed to confirm [18F]FEPPA PET findings in stroke." (PMID 32990808, 2020). "Wild-type rats subsequently received an endothelin-1 (ET1) subcortical stroke and were imaged at days 7 and 28 post-stroke before immunohistochemistry of TSPO, GFAP, iNOS, and the MHCII rat antigen, OX6." (PMID 32990808, 2020). "TSPO was only expressed in the stroke-induced insult and proximal tissue and therefore was unable to detect remote and non-insult-related chronically activated microglia overexpressing MHCII in WM." (PMID 32990808, 2020). "Applying the second-generation radioligand 18F-GE180 TSPO, for PET, showed distinct patterns of upregulation of TSPO 18F-GE180 uptake in the carotid plaques of stroke patients, suggestive of activated macrophages’ infiltration." (PMID 32252470, 2020). "Our work in rats demonstrates that although TSPO detected neuroinflammation near the ET1-induced infarct, only MHCII was able to detect the WM microglial activation that occurred late post-stroke or in response to overexpression of pathogenic APP." (PMID 32990808, 2020). "All of this suggests that the cerebellum is a practical pseudoreference for rodent TSPO PET studies of stroke and AD, but others should continue to investigate and validate their choice." (PMID 32990808, 2020). "In our study, we found that ET1-induced subcortical stroke infarcts have increased TSPO uptake at days 7 and 28 post-stroke." (PMID 32990808, 2020). "As the mitochondrial TSPO is obviously a protein that is involved in various aspects of stroke, it was recognized that it can be targeted for treatment of this condition." (PMID 32252470, 2020). "Our study similarly demonstrated that after day 7, iNOS increases while TSPO decreases, albeit insignificant partly due to high variability in rodent post-stroke iNOS expression." (PMID 32990808, 2020). "Our findings are consistent with previous reports in different rodent models of stroke demonstrating increased ipsilateral uptake using TSPO PET." (PMID 29976695, 2019).
Stroke (continued). "Stroke researchers have utilised TSPO PET imaging to understand the role and time course of neuroinflammation following acute cerebral infarction." (PMID 31139952, 2019). "The baseline fasting plasma TSPO level was assessed within 24 h after the incident stroke and during hospitalization (on days 8–10)." (PMID 30034558, 2018). "The low expression level of TSPO under physiology condition in the brain regions coupled with the dramatic upregulation induced by brain ischemia enables TSPO to serve as a suitable candidate to monitor inflammation after stroke onset." (PMID 28754131, 2017). "Most of the previous preclinical studies testing second-generation TSPO tracers have primarily used either acute excitotoxic lesion models or models of stroke relevant to the strong levels of NI observed in stroke or brain trauma." (PMID 27481358, 2017). "The translocator protein (TSPO) is an important target for imaging focal neuroinflammation in diseases such as brain cancer, stroke and neurodegeneration, but current tracers for non-invasive imaging of TSPO have important limitations." (PMID 29142713, 2015). "Positron emission tomography (PET) has been used to label inflammatory cells in stroke patients using the radioligands 11C(R)-PK11195 for the translocator protein 18kDa (TSPO), commonly used as a microglial marker." (PMID 25642168, 2014). "Since then [18F]DPA-714 has been used to follow the time-course of TSPO expression following experimental stroke in rats, and yielded results similar to those described previously with PK11195." (PMID 23418569, 2013). "TSPO expression has been detected robustly after stroke in experimental animal models and patients, so we compared [11C]PK11195 and [18F]DPA-714 after focal cerebral ischaemia in rats using in vivo PET imaging." (PMID 23418569, 2013). "In other pathologies, such as traumatic brain injury, stroke or Parkinson’s disease, the use of agonist and antagonist ligands of TSPO exhibited beneficial effects, making the simple antagonist/agonist definition insufficient to understand the effects of TSPO ligands." (PMID 41152868, 2025). "Specifically, TSPO PET imaging showed elevated binding in the acute phase of stroke distant from the infarct area (e.g., thalamus, hippocampi, amygdalae, and midbrain), which gradually decreased over time, suggesting resolution of inflammation when compared with day 15 (mean SD g/mL 0.89; P = 0.04)." (PMID 39224610, 2024). "Our findings provide scientific rationale to support that TSPO imaging provides a valuable tool to study the neuroinflammatory response in stroke and allows for assessment of immunomodulatory treatments targeting inflammation in pre-clinical and clinical settings." (PMID 37193998, 2023). "Conversely, [18F]CPFPX (A1 adenosine receptor, A1AR) followed an inverse pattern to TSPO levels along time with an early decrease 24 h post-stroke returning to baseline at day 3 followed by a subsequent progressive decrease reaching significance vs baseline at days 21–28 post-MCAO." (PMID 34245328, 2021). "Overall, that review covered clinical studies investigating (i) TSPO after stroke using [11C]-R-PK11195, (ii) preclinical studies in primates using a clinical scanner and [11C]-R-PK11195 as well as (iii) the first preclinical studies using small animal dedicated scanners." (PMID 34245328, 2021). "Altogether, these first studies were extremely helpful to demonstrate the importance of neuroinflammation after stroke and the value of TSPO-PET imaging to quantify it, and they provided invaluable information in terms of the study design to future preclinical and clinical studies." (PMID 34245328, 2021). "Considering the numerous reports showing that it takes approximately 3 days for microglia to proliferate and TSPO expression to increase in stroke and LPS model of neuroinflammation, unsurprisingly this study did not detect any significant change in [18F]GE-180 between 5 and 32 h post-hypoxia." (PMID 34245328, 2021).